TIMP3 (TIMP metallopeptidase inhibitor 3)
Diseases named in the same sentence as TIMP3 in open-access papers (continued):
Sharing a sentence is not in itself a finding about the gene and the disease.
Stroke (4 papers, 2018 to 2022). Sudden impairment of blood flow to a part of the brain due to occlusion or rupture of an artery to the brain. "TIMP-3 forms complexes with NOTCH-3 and accumulates in the extracellular matrix of brain vessels of patients and mice with CADASIL, an inherited cerebral small vessel disease and a cause of stroke and dementia." (PMID 35629249, 2022). "However, we cannot exclude that the increasing expression of Timp-2, Timp-3 and Timp-4 mRNA also facilitates brain repair after a stroke by increasing cell proliferation and/or differentiation." (PMID 30062663, 2019). "Similarly, Timp3 and Neuroserpin are upregulated in penumbral cortical neurons following stroke in the ipsilateral hemisphere." (PMID 28290150, 2018). "In the contralateral hemisphere, Adamts4 mRNA expression was upregulated after stroke, but not after stroke and EE conditions, a tendency also seen in Timp3 and Neuroserpin." (PMID 28290150, 2018). "In order to discern if the increased activity of MMP-9 and tPA that we see in the stroke EE group was due to changes in expression of respective ECM proteases, mRNA levels of Mmp9, as well as Adamts4, Tpa, and their inhibitors (respectively, Timp1, Timp3, and Neuroserpin) were studied by RT-qPCR." (PMID 28290150, 2018).
asthma (3 papers, 2014 to 2017). "Ratios of MMP-9/TIMP-3 were decreased in both uncontrolled and controlled asthma compared to healthy controls." (PMID 24950767, 2014). "This was evidenced, for example, by greater expression of TIMP3, an inhibitor of extracellular matrix degradation, and CHI3L1, a secreted glycoprotein also thought to drive tissue remodelling and a known genetic risk factor for asthma severity." (PMID 28061811, 2017).
astrocytoma (3 papers, 2007 to 2015). "Several of these genes, including MYC, EGFR, HIF1A, HGF, APOE, TIMP3, and WNT5A have been identified as being important to development of astrocytoma." (PMID 23737970, 2013). "We examined the mRNA expression profiles of RECK transcripts, as well as of MMPs reportedly inhibited by canonical RECK (MMP-2, -9 and -14), and of endogenous tissue inhibitors of MMPs (TIMP-1, TIMP-2, TIMP-3 and TIMP-4) in astrocytomas of different grades of malignancy." (PMID 26431549, 2015).
atrial fibrillation (3 papers, 2013 to 2023). A disorder characterized by an electrocardiographic finding of a supraventricular arrhythmia characterized by the replacement of consistent P waves by rapid oscillations or fibrillatory waves that vary in size, shape and timing and are accompanied by an irregular ventricular response. "Timp3 is a regulator of adult myogenesis implicated in the fibrotic pathological remodeling of infarcted heart, and in atrial fibrillation." (PMID 23300973, 2013).
brain injury (3 papers, 2018 to 2021). Acute and chronic (see also brain INJURIES, CHRONIC) injuries to the brain, including the cerebral hemispheres, CEREBELLUM, and brain STEM. "The secretion of TIMPs (such as TIMP-3) by MSCs has been the suggested mechanism of intravenous cell delivery in a model of traumatic brain injury." (PMID 30075797, 2018). "The association between TIMP-3 levels and clinical outcomes was not attenuated by measures of severity of brain injury or shock on arrival to the ED." (PMID 30023434, 2018).
CADASIL (3 papers, 2016 to 2022). "Collectively, these findings support the concept that the diminished myogenic tone and CBF deficits in CADASIL are caused by TIMP3-mediated suppression of the ADAM17/HB-EGF/(ErbB1/ErbB4) pathway." (PMID 27476853, 2016). "Moreover, elevated TIMP-3 was also observed in brain vessels of cerebral autosomal dominant arteriopathy with subcortical infarcts and leukoencephalopathy (CADASIL)." (PMID 35629249, 2022).
esophageal squamous cell carcinoma (3 papers, 2016 to 2020). Esophageal squamous cell carcinoma (ESCC) is a type of esophageal carcinoma (EC) that can affect any part of the esophagus, but is usually located in the upper or middle third. "In human esophageal SCC, the protein expression of p16, RAR-β2, and TIMP3 is decreased, and ERCC1 and BRCA1 protein expression varies." (PMID 27410681, 2016).
gastric adenocarcinoma (3 papers, 2013 to 2019). "In this study, we assessed the relationship among the aberrant methylation of the promoter CpG islands of tissue inhibitor of metalloproteinase 3 (TIMP3) gene, its protein expression, and the clinicopathological features of gastric adenocarcinoma." (PMID 23819566, 2013). "The methylation status of the promoter CpG islands and the protein expression of TIMP3 gene in tumors and adjacent normal mucosal tissues of 78 patients with gastric adenocarcinoma were detected by methylation-specific PCR (MSP) and immunohistochemistry." (PMID 23819566, 2013). "We explored the correlation of gene promoter methylation with its corresponding protein expression and then analyzed the relationship of TIMP3 gene CpG island abnormal methylation with the development, as well as clinical and pathological features, of gastric adenocarcinoma." (PMID 23819566, 2013).
geographic atrophy (3 papers, 2021 to 2022). "Recent studies demonstrate significant differences in plasma concentrations of MMP-9, TIMP-1, and TIMP-3 proteins in patients with AMD: higher levels of TIMP-1 and MMP-9 in patients with geographic atrophy (GA) and lower levels of TIMP-3 and lower TIMP-3/MMP-2 ratios in patients with CNV." (PMID 35155457, 2021). "In addition, plasma levels of TIMP-1 and MMP-9 proteins are elevated in patients with geographic atrophy, one of the late stages of AMD, while TIMP-3 and TIMP-3/MMP-2 ratios are lowered in subjects with AMD with choroidal neovascularization." (PMID 35457074, 2022).
injury (3 papers, 2018 to 2025). Damage inflicted on the body as the direct or indirect result of an external force, with or without disruption of structural continuity. "TIMP3, a neuroprotective protein, enhances neuronal survival and outgrowth, with potential therapeutic effects in traumatic brain injury." (PMID 40438583, 2025).
invasive breast carcinoma (3 papers, 2006 to 2025). A carcinoma that infiltrates the breast parenchyma. "Hypermethylation of TIMP3 in invasive breast cancer might be associated with high tumor grading and metastasis." (PMID 35150338, 2022). "Our aim was to study the expression pattern of tissue inhibitor of metalloproteinases (TIMP)-3 protein in invasive breast carcinoma, and its clinicopathological and prognostic value as well as its relation to markers indicative of the tumor phenotype." (PMID 17032447, 2006). "The Breast Invasive Carcinoma TCGA PanCancer Atlas dataset was used to identify 48 VPP cases and 66 VPW cases based on the expression of VCAN, ADAMTS4, and TIMP3." (PMID 40361362, 2025).
kidney cancer (3 papers, 2014 to 2025). Primary or metastatic malignant neoplasm involving the kidney. "TIMP-3 is associated with a variety of cancers, including kidney cancer and brain cancer, and the methylation-related silencing of the TIMP-3 gene indicates its inhibitory effect on cancer progression." (PMID 37823051, 2023). "For kidney cancer, a maximum sensitivity and specificity of 88% and 100%, respectively, were found for VHL, p16/CDKN2a, p14ARF, APC, RASSF1A, and Timp-3." (PMID 40141826, 2025).
metastatic melanoma (3 papers, 2012 to 2024). A melanoma that has spread from its primary site to another anatomic site. "Surface levels of some TNF receptor family members have been suggested to be affected by enforced expression of TIMP-3 in metastatic melanoma cell lines." (PMID 22389670, 2012). "Enforced expression of tissue inhibitor of metalloproteinases-3 (TIMP-3), an endogenous inhibitor for TACE, has been reported to up-modulate surface levels of some TNF receptor family members including DR4 and Fas in metastatic melanoma cell lines." (PMID 22389670, 2012).
ovarian tumors (3 papers, 2014 to 2025). "Downregulation of TIMP3 was also observed in ovarian tumors obtained after adjuvant chemotherapy." (PMID 24804215, 2014). "We examined the expressions of TIMP3, BRAF, and ITGB1 in ovarian tumor samples from both the LLU cohort and, subsequently, confirmed these findings using the TCGA database, stratified by race." (PMID 41294900, 2025). "Contrary to the immunohistochemistry expression of TIMP-1 in ovarian tumors, the concentration of TIMP-1, measured by ELISA, was much higher than the concentrations of TIMP-2 and TIMP-3 (***p>0.0001 vs TIMP-3; *p>0.05 vs TIMP-2) in the ascites of CN patients." (PMID 35047406, 2021).
retinitis pigmentosa (3 papers, 2022 to 2025). Retinitis pigmentosa (RP) is an inherited retinal dystrophy leading to progressive loss of the photoreceptors and retinal pigment epithelium and resulting in blindness usually after several decades. "Vessel density was found to be highest in EFEMP1, BEST1, TIMP3, RS1, and PRPH2 (11.0%, 10.4%, 10.1%, 10.1%, 9.2%) and was lower in retinitis pigmentosa (RP) and Leber congenital amaurosis genes." (PMID 39896422, 2025).
Sepsis (3 papers, 2011 to 2023). Sepsis is defined as life-threatening organ dysfunction caused by a dysregulated host response to infection. "TIMP-3 may act in a similar manner as TIMP-3-deficient mice were protected from sepsis-induced pulmonary inflammation and remodelling." (PMID 21547259, 2011). "Timp3-null mice displayed higher pulmonary microvascular leakage after sepsis, leading to tissue edema and multiple organ dysfunction." (PMID 35207132, 2022). "TIMP-3 controls the microvascular endothelial cell barrier function, as was shown in a model of sepsis induced by caecal-ligation and perforation." (PMID 35207132, 2022). "We found that sepsis enhanced the expression of E‐cadherin, ZO‐1, MMP2, and MMP9 but weakened that of TIMP‐2 and TIMP‐3." (PMID 37525933, 2023).
steatosis (3 papers, 2011 to 2023). Increased lipid within the cytoplasm of cells. "Genes encoding ECM-regulating proteins, such as Timp3, which have been shown to be protective in steatosis and HCC when overexpressed in hepatocytes, were downregulated in our study." (PMID 37415213, 2023). "In another study, mice double-heterozygous for the insulin receptor and Timp3 that were placed on a high fat diet developed macrovesicular steatosis and showed a higher degree of hepatic and adipose tissue inflammation compared to wild-type mice." (PMID 21980496, 2011). "In contrast, Timp3 deficient animals fed a high fat diet for five months experienced increased TACE activity, became glucose-intolerant and insulin-resistant and developed severe macrovesicular steatosis compared to wild-type mice." (PMID 21980496, 2011).
thyroid tumor (3 papers, 2019 to 2022). A benign or malignant neoplasm affecting the thyroid gland. "To have a broader view on the mediators of TIMP3 oncosuppressor activity in thyroid tumors, we focused on the TIMP3 related transcriptome." (PMID 36503426, 2022). "In summary, our results highlight that the expression level of TIMP3 in thyroid tumor cells is likely to transcriptionally regulate several processes including inflammation and tumor immune infiltration." (PMID 36503426, 2022). "Thyroid tumors with TIMP3-high expression showed a down-modulation of inflammation-related gene sets, along with a reduced protumoral hematopoietic cells fraction; an enrichment of cell adhesion functions was also identified." (PMID 36503426, 2022). "To get a deeper insight on the mediators of TIMP3 oncosuppressor activity in thyroid tumors, here we focused on the TIMP3 related transcriptome." (PMID 36503426, 2022). "In thyroid tumors TIMP3 methylation, and hence its downregulation, has been reported and also found significantly associated with several aggressive features of PTC, including extrathyroidal invasion, lymph node metastasis, multifocality, advanced tumor stages and BRAFV600E mutation." (PMID 36503426, 2022). "In a previous study, TIMP3 was reported to modulate the adhesion ability in thyroid tumor cells." (PMID 31624299, 2019).
Turner syndrome (3 papers, 2018 to 2025). Turner syndrome is a chromosomal disorder associated with the complete or partial absence of an X chromosome. "We propose that the combination of X chromosome TIMP1 hemizygosity and variants of its autosomal paralogue TIMP3, significantly increases the risk of aortopathy in Turner syndrome." (PMID 30281655, 2018). "This study of a discovery cohort of 188 and a replication cohort of 53 individuals with Turner syndrome identified an exome-wide significant association between TIMP3 (MIM: 188826) and BAV/TAD." (PMID 30281655, 2018). "Analysis of individuals with Turner syndrome with varying second sex chromosome karyotypes showed that the combined loss of TIMP1 and the presence of the TIMP3 risk allele significantly increased risk for BAVD." (PMID 34821691, 2021). "The inherent decrease in TIMP1 in Turner syndrome subjects missing a complete second copy of the X chromosome sensitizes those individuals to decreased TIMP3 expression." (PMID 30281655, 2018). "Loss of TIMP3 expression may be compensated for by an increase in TIMP1, which cannot occur in Turner syndrome when there is hemizygosity of TIMP1." (PMID 34821691, 2021). "This demonstrates a TIMP3-driven association between BAV and aortic enlargement in Turner syndrome." (PMID 30281655, 2018). "Attributes of Turner syndrome subjects with or without TIMP3 rs11547635." (PMID 30281655, 2018).
acne (2 papers, 2024). An inflammatory process of the sebaceous glands which is characterized by comedones, nodules, papules and/or pustules on the skin. "The biological annotation analysis indicates that we have identified 3 pairs of associated genes between gut microbiota and acne vulgaris, including PLA2G4A/FADS2, TIMP3/ADAMTS9 and ZC3H3/CPSF4L." (PMID 38371936, 2024). "By modulating key structural genes like ELN, FN1, EGFR, and TIMP3, F3TAC supports ECM remodeling and wound healing, essential for addressing inflammation and tissue repair in acne-prone skin." (PMID 39684852, 2024).
acute respiratory distress syndrome (2 papers, 2018 to 2022). Progressive and life-threatening pulmonary distress in the absence of an underlying pulmonary condition, usually following major trauma or surgery. "Plasma TIMP-3 levels were lower in patients with oral squamous cell carcinoma and higher among subjects who developed acute respiratory distress syndrome." (PMID 35629249, 2022).
adenoma (2 papers, 1997 to 2014). A neoplasm arising from the epithelium. "In this study, we report on the distribution of tissue inhibitor of matrix metalloproteinase-3 (TIMP-3) mRNA expression in human normal colorectal mucosa, adenomas and adenocarcinomas." (PMID 9184186, 1997). "ESR1 has been shown to occur in histologically normal colon epithelium in an age dependent fashion, CDH13 is also frequently methylated in CRC and seems to be correlated with the adenoma-carcinoma transition, like other genes with methylation frequencies > 30% (CDKN2B, RASSF1, RARB, APC and TIMP3)." (PMID 25091577, 2014).
anaplastic meningioma (2 papers, 2014 to 2016). A WHO grade III meningioma characterized by the presence of malignant morphologic features, including malignant cytology and a very high mitotic index (20 or more mitoses per ten high power fields). "Interestingly, loss of chromosome 1p - as an important genetic prognostic marker in meningiomas – and also loss of 9p – a typical chromosomal aberration in anaplastic meningiomas – did not accompany hypermethylation of TIMP3." (PMID 24722350, 2014).
aortic regurgitation (2 papers, 2012 to 2023). "Very recently, the rs11547635 variant (22:32857305:C-T) in TIMP3 has also been associated with aortic regurgitation in a longer term follow up study of Turner women." (PMID 37800145, 2023). "The BAV group with aortic valve insufficiency had increased TIMP-3 levels in area 23II than in area 1 (P = 0.02)." (PMID 22645456, 2012). "BAV patients with aortic valve insufficiency had increased TIMP-3 levels in aortic area 23II when compared with those in TAV patients with aortic valve insufficiency (P = 0.03)." (PMID 22645456, 2012). "The BAV group with aortic valve insufficiency had elevated TIMP-3 levels in the convex aortic sites than in the concave aortic sites." (PMID 22645456, 2012). "In contrast to TAV patients with aortic valve insufficiency, BAV patients with insufficiency had increased TIMP-3 concentrations in the convex aortic sites." (PMID 22645456, 2012).
autoimmune hepatitis (2 papers, 2013 to 2022). Hepatitis caused by autoantibodies. "Timp3-null mice challenged with intravenous administration of concavalin A to develop autoimmune hepatitis displayed enhanced activation of hepatic T-cells, cytokine release and, ultimately, increased mortality." (PMID 35207132, 2022). "Murthy and colleagues found that TIMP-3 has a broader role in immunity using a murine model of autoimmune hepatitis in which inflammation is not only driven by canonical immune cells but also epithelial and stromal cells of the liver, such as hepatocytes, endothelial cells and stellate cells." (PMID 35207132, 2022). "Furthermore, stromal TIMP-3 has recently been show to regulate basal lymphocyte populations in liver tissue and prevent autoimmune hepatitis providing further evidence for the role of TIMP-3 in regulation of inflammation." (PMID 23468994, 2013).
brain hemorrhage (2 papers, 2021 to 2024). "In one study, reducing the expression of pericyte Alk-5, a TGFβ receptor, lead to reduced TIMP-3 expression and increased brain hemorrhages." (PMID 39544367, 2024).
breast adenocarcinoma (2 papers, 2002 to 2017). "Inhibition of miRNA-221/222 in ER-positive human breast adenocarcinoma cell line (MCF-7) can also increase the sensitivity to tamoxifen through the upregulation of tissue inhibitor of metalloproteinases-3 (TIMP3)." (PMID 28261196, 2017). "Furthermore, NO promotes tumour cell invasion in the C3L5 murine mammary adenocarcinoma model by altering the balance between the expression of matrix metalloproteinase-2 (MMP-2) and it's tissue inhibitors-2 and -3 (TIMP 2 and TIMP 3)." (PMID 11953890, 2002).
bronchiectasis (2 papers, 2016 to 2019). Segmental, irreversible dilation of the bronchial tree resulting in the accumulation of secretions which leads to obstruction. "The TIMP3 gene should be screened in familial pulmonary diseases with bronchiectasis, associated with a medical history of visual loss." (PMID 27601084, 2016). "Similarly, both members of the second family (carrying the TIMP-3 p.S38C mutation) exhibited moderate bronchiectasis." (PMID 31877820, 2019).
Cerebral ischemia (2 papers, 2013 to 2022). Restriction of arterial blood supply to the brain associated with insufficient oxygenation to support the metabolic requirements of the tissue. "For MMP-3 and TIMP-3 a trend for the association with cerebral ischemia was observed (p = 0,06 and p = 0.054)." (PMID 23555845, 2013). "The ability of TIMP-3 to induce apoptosis has been investigated in vivo in neuronal cell death following cerebral ischemia." (PMID 35207132, 2022).
choroidal neovascularization (2 papers, 2014 to 2022). An eye disorder described by the growth of new blood vessels that originate from the choroid through a break in the Bruch membrane into the sub–retinal pigment epithelium (sub-RPE) or subretinal space. "Exons of TIMP3 were also sequenced in BCD patient associated with choroidal neovascularization (CNV)." (PMID 24739949, 2014).